FBXO11 (F-box protein 11)
Diseases named in the same sentence as FBXO11 in open-access papers (continued):
Sharing a sentence is not in itself a finding about the gene and the disease.
tumor (36 papers, 2013 to 2026). "Increased expression of FBXO11 has been associated with enhanced tumor aggressiveness, including larger tumor size, LN metastasis, and advanced clinical stage." (PMID 40740483, 2025). "The carcinogenic role of tobacco smoke is supported by our observation of DBS2-matching doublet mutations occurring in tumor suppressor genes FBXO11 and TGFBR2 in the samples of two individuals with a smoking history." (PMID 38711096, 2024). "FBXO11 can regulate the invasive metastasis of tumor cells by associating with the EMT-related factor Snail, as well as the classical PI3k/Akt signaling pathway." (PMID 39409891, 2024). "We consider a causative relationship with the germline deletion of FBXO11, a haplo-insufficient tumor suppressor in this cancer type, conceivable." (PMID 33811277, 2021). "A tumor-suppressor role for FBXO11 was first discovered in DLBCL, where it is mutated in up to 10% of cases and selectively ubiquitinates the germinal-center transcription factor BCL6 leading to its degradation." (PMID 33024076, 2020). "Our study found that methylation of FBOX11 was associated with worse survival which supported that FBXO11 acted as a tumor suppressor." (PMID 32489454, 2020). "However, other studies showed that FBXO11 acted as a tumor suppressor and higher expression of FBXO11 was associated with better patient survival 41-43." (PMID 32489454, 2020). "Given the tumor-suppressive functions of FBXO11 in hematologic malignancies, we queried whole-exome sequencing data from the Memorial Sloan Kettering Cancer Center (MSK) IMPACT-HEME study for FBXO11 mutations." (PMID 41542766, 2026). "It is noteworthy that the impact of FBXO11 expression on tumor grade is more likely to be seen in the early stages (I–II) of the tumor, when cancer cells are about to develop and have spread to a small extent." (PMID 39409891, 2024). "FBXO11 exerts crucial regulatory functions in cell cycle regulation, tumorigenesis, and metastasis of tumor cells through its ability to bind to substrate proteins and facilitate their degradation." (PMID 38864622, 2024). "Seven heterozygous protein-truncating mutations were found in tumor suppressor genes including RB1, FBXO11, FAT1, KMT2D, KMD6A, ACVR2A and ZFHX3." (PMID 36702998, 2023). "Although numerous studies suggesting the involvement of FBXO11 in tumor progression, PRMT9-mediated arginine methylation modifications in tumors have not been studied much, limited by the short time frame of the studies." (PMID 37715221, 2023). "The low tumor penetrance indicates that additional alterations are required for full transformation, along with FBXO11 inactivation." (PMID 34456919, 2021). "This past year, emerging evidence from exome and RNA-sequencing data suggests that FBXO11-inactivating mutations occur in de novo AML12, supporting our model of FBXO11 as a tumor suppressor in myeloid malignancies." (PMID 33024076, 2020). "Numerous studies show that miR-21-5p promotes carcinogenesis and tumor progression by targeting genes encoding PDCD4, PTEN, BTG2, FasL, IGFBP3, TGF-β1, FBXO11, and TIMP3." (PMID 33396321, 2020). "We report here that loss of the F-Box protein FBXO11, a component of the SCF ubiquitin ligase complex, confers cytokine independent growth to MDS-L cells, suggesting a tumor suppressor role for FBXO11 in myeloid malignancies." (PMID 33024076, 2020). "In this study, we performed a genome-wide CRISPR-knockout screen for cytokine-independent survival of the MDS-L human cell line and identified FBXO11 as a potential tumor suppressor in MDS and secondary AML." (PMID 33024076, 2020). "To identify a direct molecular mechanism for the tumor-suppressor-like function of FBXO11 in MDS, we performed a global quantitative ubiquitin-capture proteomic screen in the MDS-L model." (PMID 33024076, 2020).
tumor (continued). "Correlation analysis showed that tumour differentiation status was positively correlated with FBXO11 expression, indicating a higher probability of FBXO11 overexpression in poorly or moderately differentiated tumours than in highly differentiated tumours." (PMID 31159774, 2019). "FBXO11 can regulate tumour formation or progression via several processes, such as growth suppression, EMT and angiogenesis." (PMID 31159774, 2019). "To determine the clinical relevance of FBXO11 expression in ccRCC, we evaluated the in situ levels in tumour tissues resected from patients in the two cohorts." (PMID 31159774, 2019). "A total of 57.3% (86 of 150) in the training cohort and 57.1% (44 of 77) in the validation cohort of tumour tissues weas scored as having high FBXO11 staining density." (PMID 31159774, 2019). "A recent study in epithelial cancer demonstrated cells that FBXO11 induced an increase of Snai1 and a decrease of E-cadherin to prevent tumor progression, thus characterizing FBXO11 as a tumor suppressor." (PMID 28403887, 2017). "Many F-box proteins such as FBXW7, FBXL2, FBX4 and FBXO11 are found to be lost in a wide range of human cancers, and generally considered as tumor suppressor genes." (PMID 23826080, 2013). "According to early reports, FBXO11 had a tumor-suppressive effect on myeloid malignancies." (PMID 39072320, 2024). "FBXO11 plays a versatile role in cancer, acting both as an oncogene and as a tumor suppressor." (PMID 39137238, 2024). "Together, these data support the hypothesis that in PDAC, and perhaps other cancer types, the tumor-suppressive function of SAMD1 is counteracted by FBXO11." (PMID 39137238, 2024). "Nonetheless, this model confirmed a tumor-suppressor role for FBXO11 in lymphomagenesis, and could be utilized to gain further insights into the mechanism underlying the pathogenetic process." (PMID 34456919, 2021). "We hypothesize that the heterozygous germline FBXO11 deletion in the patient would result in retained BCL-6 expression in the tumor." (PMID 33811277, 2021). "Whether the FBXO11 pathway can be therapeutically targeted will require a greater understanding of its tumor-suppressor mechanism." (PMID 33024076, 2020). "Furthermore, multivariate analysis showed that higher FBXO11 levels and larger tumour size were independent prognostic indicators of worse OS in patients." (PMID 31159774, 2019). "In a number of DLBCL lines FBXO11 was found to be mutated or deleted, and restoration of FBXO11 expression in DLBCL-derived tumor cells in immunodeficient mice induced apoptosis and suppressed tumor growth." (PMID 30359271, 2018). "The oncogenic miR-21 inhibits the tumor suppressive activity of FBXO11 to promote tumorigenesis." (PMID 28060761, 2017). "To further test its role as a tumor suppressor in MDS, we overexpressed FBXO11 in F-36P and MDS92 cells." (PMID 41542766, 2026). "Tumors with FBXO11 deletion showed significant local invasion, while the results for tumors with FBXO11 and ZEB1 double knockdown were similar to those of tumors with ZEB1 single knockdown, with clear tumor boundaries." (PMID 39409891, 2024). "To explore the physiological role of FBXO11 and ZEB1 in vivo, we transplanted A549 cells into nude mice (Balb/c-nu/nu) with an immunodeficient system suitable for tumor transplantation and immunology research." (PMID 39409891, 2024). "Furthermore, NDR1 and FBXO11 overexpression significantly prolonged the survival period of tumor-bearing nude mice, but the effect on the survival period was significantly weakened when NDR1 was overexpressed and FBXO11 was knocked out or when the FBXO11 S187A mutation was introduced." (PMID 39309441, 2024).
tumor (continued). "In normal or early-stage tumor cells with low ERK3 expression, FBXO11 binds to the zinc finger domains of Snail and degrades it via the ubiquitination-proteasome system (UPS)." (PMID 38201533, 2023). "Considerable research has confirmed its activity as a tumor suppressor in HCC that inhibits proliferation, migration, and invasion by targeting F-box protein 11 (FBXO11), an E3 ubiquitin ligase, and type II methyltransferase." (PMID 31640265, 2019). "In BCs, FBXO11 restrained tumor initiation and metastasis by promoting SNAIL ubiquitylation and degradation, and overexpression of FBXO11 was correlated with longer metastasis-free survival." (PMID 30341246, 2019). "In malignant tumor cells with high expression of ERK3, ERK3 increases the stability of Snail protein by inhibiting the binding between FBXO11 and Snail, and the stabilized Snail might induce the EMT process." (PMID 38201533, 2023). "No somatic alterations in FBXO11, MSH6 or BCL6 were present, nor did we find hypermutation in the tumor or a mutational signature related to MMR deficiency." (PMID 33811277, 2021).
cancer (19 papers, 2013 to 2026). A tumor composed of atypical neoplastic, often pleomorphic cells that invade other tissues. "FBXO11 variants were also identified in human cancers, such as colon, lung, ovary, and head and neck tumors." (PMID 34946970, 2021). "Interestingly, somatic FBXO11 missense variants found in various cancer cell lines are mostly affecting CASH domains, are also predicted to lead to a loss of FBXO11 function, but are unique from germline variants seen in NDDs." (PMID 34505148, 2022). "In summary, our findings provide insights into the regulation of EMT-related genes in PDAC, shedding light on the intricate role of SAMD1 and its interplay with FBXO11 in this cancer type." (PMID 39137238, 2024). "More research will be necessary to clarify the detailed processes of how the FBXO11 E3 ubiquitin ligase complex influences SAMD1 function in the cells, and how this role contributes to the overall function of FBXO11 in cancer cells." (PMID 39137238, 2024). "Together, our study offers novel insights into the control of EMT-related genes in PDAC, revealing the intricate involvement of SAMD1 and its interplay with FBXO11 in this cancer type." (PMID 39137238, 2024). "Our work suggests that FBXO11 inhibits SAMD1 chromatin association, which represents a novel regulatory mechanism of FBXO11 in cancer." (PMID 39137238, 2024). "Top expressed cancer-implicated gene targets for each TF converged on notable genes involved in cell signaling (SMAD3, PTPRJ), BCL6 regulation (FBXO11, BCOR), and transcriptional regulation (RUNX1, ERG, CUX1)." (PMID 38116118, 2023). "Considering that targets can modulate in GC, we investigated the differential expression of two targets (CREBZF and FBXO11) with three miRNAs (hsa-miR-421, hsa-miR-29b-1-5p, hsa-miR-27b-5p) using two different cancer cell lines (SNU-NCC-9 and MKN74)." (PMID 32218690, 2020). "FBXO11 expression was significantly lower in normal tissues than in cancer tissues (23 ccRCC and 11 pRCC samples) (P < 0.001, F = 14.03)." (PMID 31159774, 2019). "Based on its established oncogenic role in various cancer models, FBXO11 likely contributes to ccRCC progression." (PMID 31159774, 2019). "In addition, FBXO11 expression was also significantly higher in metastatic kidney cancer than in primary cancer." (PMID 31159774, 2019). "In addition, FBXO11 expression was significantly higher in the metastatic tissues than in the primary cancer tissues (P = 0.002, F = 9.474)." (PMID 31159774, 2019). "FBXO11 variants occur in 1.8% of all non-AML cancers in the TCGA dataset." (PMID 41289019, 2026). "So far, germline aberrations in FBXO11 have not been linked to cancer development." (PMID 33811277, 2021). "However, a relation between somatic FBXO11 alterations and cancer has been described." (PMID 33811277, 2021). "In the present study, we first examined FBXO11 expression levels in normal and malignant renal tissues using datasets available through ONCOMINE, a web-based cancer microarray database." (PMID 31159774, 2019). "In summary, FBXO2 promotes EMT, while FBXO11, FBXO45, FBXO22, and FBXO31 inhibit EMT in human cancer cells." (PMID 30999935, 2019). "Thus far, no cancer attributed to the FBXO11 aberration has been reported in a total of 71 patients with germline FBXO11 alterations." (PMID 33811277, 2021). "For examples, protein FBXO11 has both the E3 ubiquitin ligase and methyltrasferase activity, which could facilitate epithelial-mesenchymal transition (EMT), promote PI3K/AKT pathway activation, and regulate metastasis and apoptosis in human cancer." (PMID 33425983, 2020). "Among these negative-selected PCGs are F-box only protein 11 (FBXO11) and F-box/WD repeat-containing protein (FBXW7), which have been previously demonstrated to be involved in cancer immunology." (PMID 36475797, 2022).
neurodevelopmental disorder (10 papers, 2020 to 2026). A behavioral and cognitive disorder with onset during the developmental period that involves impaired or aberrant development of intellectual, motor, or social functions. "Recently, others and we identified de novo FBXO11 (F-Box only protein 11) variants as causative for a variable neurodevelopmental disorder (NDD)." (PMID 34505148, 2022). "The functional role of FBXO11 in neurodevelopmental disorders (NDDs) and neurodevelopment in general remains elusive." (PMID 34505148, 2022). "FBXO11 was prioritized as a strong ASD candidate gene, and was recently reported to be associated with a variable neurodevelopmental disorder." (PMID 33133139, 2020).
hematologic malignancies (1 paper, 2026). "Here, we screened patients with hematologic malignancies from the MSK-IMPACT-HEME study and uncovered what we believe to be novel FBXO11 mutations in a previously undiscovered IDR in its N-terminus." (PMID 41542766, 2026).
neurological disorders (1 paper, 2022). "Fbxo11 was shown to be involved in several neurological disorders." (PMID 35893036, 2022).
skin disorder (1 paper, 2019). Any deviation from the normal structure or function of the skin or subcutaneous tissue that is manifested by a characteristic set of symptoms and signs. "The FBXO11 gene was first described as the vitiligo gene (VIT1) located on chromosome 2p21 and downregulated in vitiligo, a skin disorder characterized by the loss of melanocytes." (PMID 31159774, 2019).
FBXO11 also shares sentences with these, for which no sentence is quoted: myelodysplastic syndrome (3 papers); colon cancer (2); infection (2); liver cancer (2); Cirrhosis (1); colitis (1); congenital hydrocephalus (1); craniosynostosis (1); follicular lymphoma (1); head and neck cancer (1); head and neck tumors (1); kidney cancer (1); Macrocephaly (1); neuroblastoma (1); Obesity (1); osteosarcoma (1); Otitis (1); ovarian carcinoma (1); papillary renal cell carcinoma (1); renal cell carcinoma (1); thymoma (1); Turner syndrome (1); Wilms tumor (1); ZIKV infection (1).